IDO1 (indoleamine 2,3-dioxygenase 1)
Diseases named in the same sentence as IDO1 in open-access papers (continued):
Sharing a sentence is not in itself a finding about the gene and the disease.
Autoimmunity (continued). "Thus, further characterization of the synergy between IFNγ and Gal-9 during the induction of Ido1 and Ido2 is important to our understanding the pathophysiology of autoimmune disorders such as MS, Hashimoto’s disease, or rheumatoid arthritis." (PMID 27799931, 2016). "Vaccine-induced IDO1 biosynthesis and enzyme activity in human DCs suggest that kynurenines may be important for vaccine suppression of type 1 diabetes autoimmunity." (PMID 26378585, 2015). "Understanding how CTB-INS modulates IDO1 activity in human DCs will facilitate vaccine efficacy and safety, moving this immunosuppressive strategy closer to clinical applications for prevention of type 1 diabetes autoimmunity." (PMID 25714914, 2015). "We next evaluated whether the lack of immunosuppressive effects by TGF-β in NOD pDCs could be ascribed to inability of the cytokine to correct the defective IDO1 expression in this autoimmunity-prone strain." (PMID 25215657, 2014). "This is of particular interest since IFN-γ is commonly expressed in areas of graft rejection and inflammatory sites in patients with autoimmunity, in which Zebularine might consequently be expected to induce a synergistic, particularly strong IDO1 expression." (PMID 23991016, 2013). "Biological evaluation revealed that apoxidoles define a new potent type IV inhibitor chemotype of indoleamine 2,3‐dioxygenase 1 (IDO1), a heme‐containing enzyme considered a target for the treatment of neurodegeneration, autoimmunity and cancer." (PMID 35959923, 2022). "Although IDO2 is more narrowly expressed and less active than IDO1, IDO2 and its SNPs may also play important inhibitory roles in autoimmunity." (PMID 35045867, 2022). "In the absence of IDO1 expression, local inflammation is promoted by the engagement of a Th1-driven T-cell response as expected when autoimmunity is stimulated." (PMID 23840489, 2013). "Taken together, IDO1 and IDO2 appear to play opposing roles in inflammatory immune responses, with IDO1 an important inhibitor of effector T cell-mediated responses, especially in the context of cancer, and IDO2 a critical proinflammatory mediator of B cell-mediated autoimmunity." (PMID 32973768, 2020). "In Ido2-deficient mice, we found that genetic ablation of IDO2 but not IDO1 could phenocopy the effect of D-1MT in the context of the KRN model of RA autoimmunity." (PMID 25477879, 2014). "We suggest that IDO2 may act in a distinct manner from IDO1 as a set-point for tolerance to “altered-self” antigens along the self-non-self continuum where immune challenges from cancer and autoimmunity may arise." (PMID 25477879, 2014). "It is thus not surprising that IFNG- induced IDO-1 has also been shown to drive autoimmunity." (PMID 25928531, 2014). "Our previous work demonstrated reduced autoreactive B and T cell responses and attenuated disease in IDO2 ko, but not IDO1 ko, KRN.g7 mice, suggesting that IDO2 was an important mediator of both B and T cell responses driving autoimmunity." (PMID 32973768, 2020).
metastatic melanoma (47 papers, 2011 to 2025). A melanoma that has spread from its primary site to another anatomic site. "For example, high levels of CTLA-4, PD-1, PD-L1/2, LAG3, and IDO1 that we detected in metastatic melanoma, were many fold times more significantly associated with high cytolytic levels, pointing towards the existence of immunosuppression in these metastatic tumors." (PMID 29515971, 2018). "Phase 3 studies in metastatic melanoma were initiated by combining the IDO1 inhibitor epacodostat with pembrolizumab: however, there was no efficacy advantage." (PMID 38668043, 2024). "Primary and metastatic melanoma cells express IDO1, and its expression is promoted by in vitro stimulation with interferon-gamma." (PMID 38791968, 2024). "This active immunotherapeutic strategy has been also validated in a clinical trial, in which patients with metastatic melanoma were treated with a combinatorial IDO/PD-L1-targeting approach based on IDO1-peptide vaccine combined with nivolumab." (PMID 36161514, 2023). "The failure of the phase III trial with epacadostat in first-line metastatic melanoma is a key turning point in developing IDO1-targeting drugs." (PMID 36119020, 2022). "Recently, a first-in-class immune-modulatory vaccine (IO102/IO103) against IDO1 and PD-L1 targeting IDO1 and/or PD-L1-positive immunosuppressive cells and tumor cells was tested in combination with nivolumab in patients with naïve metastatic melanoma." (PMID 35173722, 2022). "Recently, a failure on a phase 3 trial in metastatic melanoma, based on the combination of epacadostat (IDO1 inhibitor) with pembrolizumab (anti-PD-1 antibody), generated a disappointment in the so-called “second generation” of immuno-oncology drugs (clinical trial information: NCT02752074)." (PMID 30186285, 2018). "Epacadostat is a selective IDO1 inhibitor shown to promote anti-tumor immune responses in preclinical models, however it has failed in a Phase III clinical trial for treating metastatic melanoma." (PMID 37945606, 2023). "Epacadostat (EPA), the most advanced IDO1 inhibitor, in combination with PD-1 checkpoint inhibitor, has failed in a recent Phase III clinical trial for treating metastatic melanoma." (PMID 37945606, 2023). "We evaluated the correlation of EVI2B gene expression in metastatic melanoma samples with the IFN-γ related gene signature (CXCL10, CXCL9, HLA-DRA, IDO1, IFNG, and STAT1)." (PMID 34439264, 2021). "In metastatic melanoma, PD-1, p = 1.48e−148, Pearson’s rho = 0.917; LAG3, p = 4.28e−163, Pearson’s rho = 0.931; IDO1, p = 2.38e−53, Pearson’s rho = 0.690)." (PMID 29515971, 2018). "The phase III ECHO‐301/Keynote 252 trial of Epacadostat plus pembrolizumab versus pembrolizumab alone in patients with unresectable or metastatic melanoma showed no significant benefit with IDO1 inhibition." (PMID 40910376, 2025). "A phase 1/2 study evaluating an immunomodulatory vaccine against IDO and PD-L1 combined with nivolumab (anti-PD-1 ICI) demonstrated high ORR (80%) in metastatic malignant melanoma, suggesting that targeting both IDO1 and PD-L1/PD-1 is a potential strategy to enhance the efficacy of immunotherapy." (PMID 38632994, 2024). "Most prominently, a large phase 3 trial of an IDO1 enzyme inhibitor plus a PD-1 inhibitor in metastatic melanoma did not result in greater clinical benefit compared to PD-1 inhibition alone." (PMID 36900311, 2023). "On the negative side, a phase III study combining an IDO1-selective competitive inhibitor with an anti-PD-1 monoclonal antibody failed to provide significant therapeutic gain in patients with metastatic melanoma." (PMID 32630618, 2020). "Despite a recent phase III ECHO-301 trial (NCT02752074) of PD-1 inhibitor in combination with an IDO1 inhibitor in metastatic melanoma showed no significant clinical benefit in the treatment group (pembrolizumab + epacadostat) compared with the control group (pembrolizumab + placebo)." (PMID 38267913, 2024).
metastatic melanoma (continued). "Recently, the enthusiasm with IDO1 inhibitors was dampened with the negative results of ECHO-301, a phase III trial in patients with unresectable or metastatic melanoma comparing E with P vs. P alone." (PMID 30338242, 2018). "While early clinical trials of the small molecule inhibitor of IDO1, epacadostat, in combination with the anti-PD-1 molecule pembrolizumab, showed promise, no benefit was found in a phase III trial in metastatic melanoma patients compared to pembrolizumab alone." (PMID 36765792, 2023).
cervical carcinoma (46 papers, 2011 to 2025). A carcinoma arising from either the exocervical squamous epithelium or the endocervical glandular epithelium. "In this study, we sought to elucidate the intricate association between IDO1 expression, immune infiltration, and prognosis in cervical cancer, with the ultimate goal of identifying novel therapeutic targets." (PMID 39312339, 2024). "To further demonstrate the characteristics and potential causes of differential IDO1 expression between patients with cervical cancer and healthy donors, we analyzed transcriptomics data from the GSE7410, GSE29570, GSE39001, and GSE63514 datasets." (PMID 39312339, 2024). "Incorporating a clinicopathological characteristic-based risk score model with IDO1 risk score, we devised a nomogram to predict cervical cancer patient survival." (PMID 39312339, 2024). "Despite the association of elevated IDO1 expression with unfavorable outcomes in various cancers, its precise function in cervical cancer remains ambiguous." (PMID 39312339, 2024). "Correlation analysis indicated that IDO1 expression in cervical cancer was associated with IFNG expression and the correlation coefficient was estimated to 0.63." (PMID 33390854, 2021). "Growing evidence indicates that IDO1 is overexpressed in the vast majority of solid tumors and associated with clinical prognosis, such as anal, esophageal, as well as cervical cancer." (PMID 34778035, 2021). "Accordingly, increased systemic Kyn/Trp ratio and elevated IDO1 activity have been associated with poor prognosis and low survival of patients diagnosed with cervical cancer and glioblastoma multiforme." (PMID 29445380, 2018). "A recent genomic sequencing study that combined large-scale tumor exome analysis with MHC I class prediction revealed a strong positive correlation between IDO1 expression, mutational burden, and neoantigen load in cervical cancers." (PMID 29445380, 2018). "TISIDB was employed to examine immune infiltration in cervical cancer, revealing that IDO1 levels exhibit a significantly positive association with ICOS, C10orf54, CD27, CD28, CD70, and other immunostimulatory factors, which negatively regulate the expression of CD276." (PMID 39312339, 2024). "Cox regression analyses highlighted IDO1 as the core immune gene implicated in cervical cancer." (PMID 39312339, 2024). "Notably, by measurement of tryptophan and kynurenines metabolites in serum samples of cervical cancer patients, enzymatically active IDO1 was associated with a poor clinical outcome." (PMID 30186285, 2018). "Therefore, the IFN-γ-IDO1 axis-mediated kynurenine accumulation and enhanced the phagocytosis caused by macrophages, which in turn led to the inhibition of the progression of cervical cancer possibly by upregulating the levels of autophagy in cervical cancer cells." (PMID 33390854, 2021). "We performed Kaplan–Meier survival analysis using the clinical data obtained from TCGA to determine the clinical relevance of IDO1 expression in cervical cancer." (PMID 39312339, 2024). "Our observations revealed a greater presence of IDO1 in cervical cancer tissues compared to normal tissues." (PMID 39312339, 2024). "We demonstrated the obvious expression of IDO1 and IDO2, a more recently identified novel isoform of IDO, at the human maternal–fetal interface at seven weeks of gestation obtained from hysterectomy for cervical cancer with a pregnancy in situ." (PMID 38674162, 2024). "The effects of IDO1 in immune regulation and its prognostic significance were validated using data from patients with cervical cancer obtained from The Cancer Imaging Archive database." (PMID 39312339, 2024). "Compared with that in normal cervical tissues, IDO1 expression was significantly upregulated in cervical cancer tissues and significantly correlated with cervical cancer progression and prognosis." (PMID 39312339, 2024).
cervical carcinoma (continued). "As in normal tissue, IDO1 was localized in the cytoplasm and membrane of cells in cervical cancer tissues (medium-intensity staining)." (PMID 39312339, 2024). "The expression of CD28 and FOXP3 was highly correlated, and high expression of IDO1, FOXP3, CD28, and FOXP3 was all associated with improved survival in cervical cancer." (PMID 39672307, 2024). "Compared with that in the healthy cervix, the expression of IDO1 is significantly enhanced in cervical cancer, negatively correlating with immune cell infiltration and influencing prognosis." (PMID 39312339, 2024). "While the improved survival of patients with increased expression of FOXP3 or IDO1 contradicts the role of T-cell suppression in cervical cancer, FOXP3 and IDO1 can be expressed in tumor cells." (PMID 39672307, 2024). "In the present study, IDO1 expression correlated with unfavorable outcomes and immune infiltration in cervical cancer patients." (PMID 39312339, 2024). "Our analysis revealed a significant upregulation of IDO1 in cervical carcinoma specimens when compared with healthy tissue across all examined datasets (P < .01)." (PMID 39312339, 2024). "The prevalence of IDO1-positive cells was greater in cervical cancer specimens than in healthy cervical tissue." (PMID 39312339, 2024). "Univariate and multivariate analyses revealed that elevated IDO1 expression correlates markedly with cervical cancer outcomes, suggesting it as a promising therapeutic target." (PMID 39312339, 2024). "The Cancer Imaging Archive data analysis revealed that the impact of anti-PD1 and CTLA4 therapy is more pronounced in cervical cancer patients exhibiting elevated IDO1 expression." (PMID 39312339, 2024). "In this study, the K14E7E2 mouse was used as a cervical cancer model to evaluate the inhibition of indolamine-2,3-dioxygenase 1 (IDO-1) and C-X-C chemokine receptor type 2 (CXCR-2) as potential anti-tumor targets." (PMID 37626777, 2023). "In normal cervix IDO1 is expressed only in rare glandular cells but is frequently expressed in cervical carcinomas." (PMID 37766359, 2023). "Regarding cervical cancer (CC), inhibition of IDO-1 (Navoximod) in combination with atezolizumab (PD-L1 inhibitor) has been studied in a phase 1 clinical trial (NCT02471846); however, antitumoral effectiveness was partial." (PMID 37626777, 2023). "IDO1 overexpression caused a significant increase in the LC3BII expression levels of HeLa and SiHa cells, suggesting that IDO1 promoted the induction of autophagy of cervical cancer cells." (PMID 33390854, 2021). "In turn, its derivative, LBJ-10, effectively inhibits the proliferation of cervical cancer cells in-vitro via IDO1 inhibition." (PMID 34201791, 2021). "In the present study, the role of the IFN-γ-IDO1-kynurenine pathway was investigated in the induction of autophagy of cervical cancer cells and in the regulation of macrophage function." (PMID 33390854, 2021). "In this study, we identified the IDO1 gene, by screening three cervical cancer gene expression microarrays for DEGs." (PMID 34778035, 2021). "The assessment of the role of IDO1 in cervical cancer growth progression can provide evidence for the application of IDO1 inhibitors in clinical trials." (PMID 33390854, 2021). "IFN-γ treatment and IDO1 overexpression promoted tryptophan depletion and kynurenine accumulation in cervical cancer cells." (PMID 33390854, 2021). "IDO1 induced of autophagy in cervical cancer cells, which further promoted phagocytosis and activation of macrophages in tumor tissues." (PMID 33390854, 2021). "Cervical cancer cells transfected with IDO1 overexpression lentivirus exhibited higher levels of phagocytosis compared to those of the control group." (PMID 33390854, 2021). "The gene expression profiles of TCGA and GTEx databases along with comprehensive bioinformatics analysis identified that the IDO1 gene was upregulated in cervical cancer with significant difference in expression at different N stages." (PMID 34778035, 2021).
cervical carcinoma (continued). "It turned out to be an uncompetitive IDO1 inhibitor, which potently decreases the proliferation rate of cervical cancer cells in-vitro." (PMID 34201791, 2021). "In the present study, we have demonstrated that IDO1 expression was upregulated in cervical CSCs or cervical cancer cells after irradiation." (PMID 32545442, 2020). "In the present study, we firstly found that the protein expression of IDO1 was increased in tumorspheres derived from HeLa and SiHa cervical cancer cells, and in cells after irradiation." (PMID 32545442, 2020). "Using tumorsphere cultivation for enriched CSCs, we firstly found that IDO1 was increased in HeLa and SiHa cervical cancer cells and in these two cell lines after radiation treatment." (PMID 32545442, 2020). "The bioinformatics analysis shows that IDO1 has binding targets of miR-218; we decided to study the mechanism of miR-218 functioning on IDO1 in the tumor immune escape of cervical cancer." (PMID 30314496, 2018). "By transfecting miR-218 mimics into HeLa cervical cancer cells, we observed that the overexpression of miR-218 significantly suppressed the expression of IDO1, inhibited cell viability, and promoted apoptosis of cervical cancer cells." (PMID 30314496, 2018). "In conclusion, the kyn/trp ratio in serum and IDO1 mRNA and protein expression per se in PTs cannot be used as a clear-cut biomarker for prognosis or to identify early stage cervical cancer patients eligible for clinical trials targeting IDO." (PMID 30050535, 2018). "Meanwhile, IDO1 levels were mostly upregulated in cervical cancer specimens, and the survival rate of patients in the IDO1 high-expression group was lower than that in the IDO1 low-expression group within 2 years." (PMID 30314496, 2018). "In cervical cancer, for instance, IDO1 shows a significantly higher mRNA transcription and protein expression level than in normal cervix, and also in comparison to other cancers." (PMID 29445380, 2018). "Subsequently, we detected the mRNA expression levels of IDO1 and miR-218 in several cervical cancer cells such as HeLa, SiHa, C-33, and Caski cells." (PMID 30314496, 2018). "A hierarchical profile between IDO1 expression have been observed in different cancer types, whereupon endometrial and cervical cancer had the highest and most frequent IDO1 expression." (PMID 30186285, 2018). "Thirty-seven cervical cancer tissues were collected and detected, and we found that miR-218 was upregulated, while IDO1 was downregulated and that the two were negatively correlated with each other." (PMID 30314496, 2018). "According to Spearman nonparametric correlation test (P = 0.0268), miR-218, and IDO1 were found to negatively correlate in cervical cancer tissues." (PMID 30314496, 2018). "A recent study using 27 cervical cancer punch biopsies showed a correlation between IDO1 mRNA levels and a high kyn/trp ratio in primary cervical cancer tissue, suggesting the presence of functionally active IDO." (PMID 30050535, 2018). "In the present study, we developed novel targeted PET imaging probes for the in vivo detection of IDO1 protein in a cervical cancer mouse model." (PMID 28159919, 2017). "In a cervical cancer patient biopsy analysis, IDO1 gene expression and kynurenine to tryptophan ratio was significantly elevated as compared to healthy controls." (PMID 29179871, 2017). "This is exemplified by cervical carcinoma, where IDO1-positive tumor cells were often located at the periphery of tumor nodules, which were surrounded by T lymphocytes." (PMID 25691885, 2015). "In both datasets, endometrial and cervical carcinomas emerged as the tumors with the highest and most frequent IDO1 expression, followed by kidney and lung carcinomas." (PMID 25691885, 2015). "While 1-D-MT did not induce de novo IDO1 mRNA expression and kyn production in IDO1-negative HeLa cervical carcinoma cells, it increased IDO1 mRNA and kyn production after induction of IDO1 expression and kyn production by IFN-γ." (PMID 21625531, 2011).